BRAF (B-Raf proto-oncogene, serine/threonine kinase)
Diseases named in the same sentence as BRAF in open-access papers (continued):
Sharing a sentence is not in itself a finding about the gene and the disease.
tumor (continued). "In this scheme, BRAF inhibition does not produce a significant antitumor effect, since tumor growth and survival become independent upon RAF–MEK–ERK signaling." (PMID 26322273, 2015). "Of note, none of the six patients with a BRAF-negative largest tumor and BRAF-positive second-largest tumor had positive lymph nodes." (PMID 26448939, 2015). "Sporadic tumours with MSI or lack of MMR protein expression also occur, so adjunctive tests such as for the BRAF V600E mutation and hypermethylation of the MLH1 promotor can reduce false-positive results." (PMID 25910169, 2015). "No mutation was identified either in BRAF (codon 600) or NRAS genes (codons 12, 13, 61 and 146) in this tumor set." (PMID 26437257, 2015). "In patients, reports indicated that BRAF-inhibitors induced tumor Ag expression and the infiltration of CD8+ and CD4+ T cells in metastases shortly after the initiation of treatment, which was followed by a reduction in tumor size." (PMID 25709607, 2015). "An additional CRC subtype comprises MSS CIN negative (diploid) tumours that also frequently are CIMP positive and BRAF mutated." (PMID 25884297, 2015). "We observed uniform hypermethylation across the Ebert region, with no differential methylation seen between BRAF mutant and BRAF wild type tumours." (PMID 26097884, 2015). "The OR for dissemination for BRAF mutated tumours is low both in MSS tumours and in KRAS wild type tumours; however these results are statistically non-significant." (PMID 25884297, 2015). "Interestingly, of the 8 PDXs that demonstrated tumor regression, 6 (75%) were KRAS/BRAF mutant and PIK3CA wild-type, whereas the other 2 were either all wild-type, or all mutant for RAS/RAF or PI3KCA." (PMID 26439693, 2015). "In the present study we analyzed the prognostic and predictive value of BRAF/KRAS mutations and tumor tissue availability in patients with non-resectable mCRC included in a prospective population-based study." (PMID 26121270, 2015). "The distribution of observed mutations was consistent with prior reports: 50% (19 of 38 patients) had a KRAS mutant tumor, 16% (6 of 38 patients) had a PIK3CA mutation, 8% (3 of 38 patients) showed a mutation in BRAF, and none showed an EGFR mutation." (PMID 25575824, 2015). "In particular, some CRC PDX models exhibited significant tumor regression, particularly those harboring mutations in KRAS and BRAF with no mutation in PIK3CA." (PMID 26439693, 2015). "Both tumor growth and tumor weight were significantly reduced in mice receiving BRAFi/AKTi combination compared to the monotherapies, confirming that AKT signaling pathway plays a role in the in vivo responses of BRAF-mutant tumors to PLX4032." (PMID 26098773, 2015). "Patients with multifocal PTC whose largest tumor is BRAF-negative can have smaller tumors that are BRAF-positive." (PMID 26448939, 2015). "Patients with BRAF mutant tumours who did not receive a BRAF inhibitor after the diagnosis of brain metastasis had a significantly worse prognosis than those who did receive such treatment." (PMID 26484413, 2015). "In this study, it was also found that BRAF fusion positive tumors had better 5-year PFS irrespective of tumor histotype or location with 5-year PFS of 65% in fusion positive PAs compared to 17% for fusion negative tumors." (PMID 25785246, 2015). "The overall findings were that the 5-year progression-free survival (PFS) was 61% in BRAF fusion positive tumors compared to 18% in fusion negative tumors (with PFS defined as greater than 25% increase in tumor volume on consecutive MRI scans)." (PMID 25785246, 2015).
tumor (continued). "Low PTEN was associated with poor survival overall but the effect was absent in BRAF and NRAS-mutated tumours, and only statistically significant in tumours without BRAF or NRAS mutations." (PMID 24830350, 2014). "There was evidence of Ras pathway activation in these tumours and cell lines with NF1 defects, in the absence of KRAS or BRAF mutations." (PMID 25026295, 2014). "MYC over-expression was significantly associated with tumor stage and MMR/BRAF IHC phenotype, but not gender, anatomic location, histologic grade, presence or absence of lymphovascular space invasion, nor peritumoral lymphocyte reaction status." (PMID 24503701, 2014). "In the here studied cohort, BRAF mutation has previously been demonstrated to be an independent factor of poor prognosis in men, but not in women, in particular in MSS tumours." (PMID 24918610, 2014). "Recent data also indicate that the prognostic value of the tumor growth pattern in stage I–III CRC is independent of central molecular features including KRAS, BRAF, and PIK3CA mutations as well as MSI-status and CIMP methylation." (PMID 24600585, 2014). "KIAA1549-BRAF fusions were found in all 9 group II tumors with BRAF duplication, but in no other group I or group II tumor." (PMID 24529209, 2014). "PCR-based DNA sequencing analysis of the patient’s tumor specimen revealed no EGFR, BRAF, KRAS, NRAS, PI3KCa, or c-kit mutations." (PMID 25126591, 2014). "Interestingly, our data on exosomal protein profiles from treated Caco-2 showed an enrichment of upregulated proteins involved in tumor etiopathogenesis, including CRC (CD59, CRP, CTSD, HMMR, LY6K, TRIM22), and in cell cycle control (BRAF, CDC2, ERBB2)." (PMID 25594007, 2014). "Compensatory PI3K pathway activation might be a serious problem in the clinical setting, where BRAF- and MEK inhibitors can encounter intrinsic as well as acquired PI3K pathway reactivation which is likely involved in tumor relapse." (PMID 24970815, 2014). "PCR-based DNA sequencing analysis of the patient’s tumor specimen revealed no EGFR, BRAF, KRAS, PI3KCa, or c-kit mutations." (PMID 25126591, 2014). "Notably, when using the co-immunoprecipitation method, endogenous BRAF and CRAF dimerization was found to be significantly enhanced in the tumor cells from the primary lung lesion and the peritoneum metastases in the present case." (PMID 25013473, 2014). "All the other cases reviewed did not present tumor genotyping so we cannot infer about the BRAF role in the other reported patients." (PMID 25988151, 2014). "BRAF V600E is activated 500-fold more than the wild-type BRAF and directly phosphorylates the ERK signaling protein in cells, which plays a dominant role in promoting angiogenesis during tumor development." (PMID 25013473, 2014). "The experience of BRAF inhibition in other tumor types suggests that response is unlikely to be uniform across all CNS tumors, even in the presence of similar V600 mutations." (PMID 24725538, 2014). "This should drive unrestrained signalling through ERK, but V600E BRAF tumour cells do not have higher levels of ERK activity than cells from other ERK-dependent tumour types." (PMID 22812510, 2013). "Tumor regression was not seen when this patient was given a multi-kinase inhibitor that did not target BRAF, or a MEK inhibitor." (PMID 23470635, 2013). "The genetics for these tumor sub-types are not yet completely understood as some groups have found that disc tumors have increased nuclear β-catenin and no KRAS or BRAF mutations, while other groups have found the opposite." (PMID 23638973, 2013). "With regard to the intra-tumor heterogeneity of BRAF V600E, only few cases with non-homogenous expression have been observed following immunohistochemical detection." (PMID 24199171, 2013).
tumor (continued). "For single gene analyses of DNA methylation profiling and validation, 19 paired tumor-normal samples were selected on presence in the ascending colon, including 8 BRAFp.V600E (6 of which were MSI-H and 2 MSS) and 11 BRAF wild types (9 of which were MSS and 2 MSI-H)." (PMID 24244575, 2013). "An additional analysis based on post-combination treatment dLMRs also resulted in clustering of patients according to BRAF tumor status (not shown)." (PMID 24047116, 2013). "Moreover, there was a strong correlation between tumor NRAS and BRAF mRNA expression levels (rs = 0.627; p < 0.001)." (PMID 23673558, 2013). "While dabrafenib can inhibit proliferation via a G1 cell cycle arrest, induce apoptosis, and cause tumor regression in BRAFV600E cells, wild-type BRAF tumor cell lines were not responsive to dabrafenib, despite MEK inhibitor sensitivity." (PMID 23844038, 2013). "It was proposed that RAS/BRAF and/or PI3K/AKT pathways are required for cellular transformation and that the additional proinflammatory pathways of RET/PTCs shape the features of the growing tumor." (PMID 24868250, 2013). "Again, no prognostic significance was found for BRAF mutation in women, either in MSS or in MSI tumours." (PMID 24020794, 2013). "Since activation or overexpression of upstream factors like KRAS or BRAF can lead to constitutive activation of ERK, this may in turn activate downstream protein kinases or transcription factors that are likely to enhance tumor development." (PMID 23644885, 2013). "Furthermore, we demonstrate that co-administration of BRAF and MEK inhibitors improves both the safety, by reducing the occurrence of skin lesions, and the in vivo activity profile, by reducing tumor regrowth, over that of a BRAF inhibitor alone in rodents." (PMID 23844038, 2013). "Whether normal gene dosage on especially chromosome 7 (containing EGFR, BRAF, cMET) is crucial for FTC-OV tumour survival is an important topic for future research." (PMID 22675538, 2012). "We hypothesized that the preferential induction of apoptosis with the combination in BRAF mutant cells suggests that combined mTOR and MEK inhibition may be particularly effective for this tumor genotype." (PMID 22808163, 2012). "KRAS is the member of the RAS gene family mostly mutated in CRC; unlike the BRAF mutations, the KRAS mutations have been found to be equally distributed in all tumours, regardless of their MSI status." (PMID 22931052, 2012). "We found that the association of disease-free survival with ATM expression is independent of tumour stage, location, use of chemo/radiotherapy, gender, KRAS/BRAF mutation status, microsatellite instability or chromosomal instability." (PMID 23154512, 2012). "The BRAF status has been shown not to vary between different tumor manifestations of the same patient." (PMID 22385786, 2012). "We conducted a univariate analysis of survival for different patient characteristics, including age, gender, race, tumor type (mucinous vs. not), Duke's stage at diagnosis, site of primary tumor, KRAS, BRAF and PIK3CA mutations." (PMID 22675430, 2012). "A mutation in the BRAF oncogene occurs in approximately 10% of mCRC patients and is restricted to KRAS wild-type tumours, and was first shown to have a negative predictive value for anti-EGFR therapy." (PMID 22804917, 2012). "It suppressed tumors containing BRAF mutant genes but not WT BRAF tumors in mice tumor xenograft studies." (PMID 23085539, 2012). "In vitro apoptosis assay results were predictive of in vivo drug efficacy as tumor regressions were observed only in a BRAF mutant xenograft model, but not GNAQ mutant model." (PMID 22808163, 2012). "Because of the oncogenic roles of activated BRAF, RET, and RET/PTC kinases, the hypothesis that specific targeting of these kinases could block tumor growth was suggested." (PMID 23133451, 2012).
tumor (continued). "In BRAF evaluated patient, BRAF mutant had a longer median progression free survival than BRAF wide-type tumor, though it was not statistically significant (33 versus 11 weeks, P = 0.3)." (PMID 23320248, 2012). "Therefore, the occurrence of functional integrity of the RAS-driven pathways - BRAF-MEK-ERK and PIK3CA-AKT - is necessary in order to really interfere with tumour cell growth through inhibition of EGFR target." (PMID 22931052, 2012). "Unsupervised clustering analysis of the resulting phosphorylation of 102 array substrates defined two tumor classes, both consisting of cases with and without KRAS/BRAF mutations." (PMID 23226389, 2012). "KRAS and BRAF mutations were mutually exclusive except in one patient (who had a pCR and therefore further tissue was not available) in which the tumor was positive for both KRAS and BRAF mutations." (PMID 21910869, 2011). "Unlike KRAS and BRAF, mutations in RHO genes are extremely rare in tumours, but their expression and/or activity is frequently altered in a variety of human cancers." (PMID 21943101, 2011). "Despite BRAF V600E-positive PXA occurring more frequently in males in our cohort, the association between tumor mutational status and gender was not significant (p value 0.36)." (PMID 21479234, 2011). "This contrasted to 12 tumours with MSI and MLH1 methylation, of which 7 had no other genetic defect or a BRAF mutation (P = 0.0099)." (PMID 21901162, 2011). "If the increase in tumor antigen expression proves to be the primary therapeutic mechanism of IFN-α, then this would also provide rationale for further investigation into IFN-α in combination with BRAF inhibitors." (PMID 24213115, 2011). "One third of the patients with wt-KRAS or mt-BRAF tumour still respond to the treatment ̧ alluding that the BRAF status is not predictive for the response to anti-EGFR antibody therapy." (PMID 22933967, 2011). "Our results suggest that only patients with mutant BRAF-V600K/E should be selected for treatment and that patients should be monitored for any secondary tumors that may not carry the BRAF mutation, or for recurrences of tumor cells that have lost the mutant BRAF allele." (PMID 20149136, 2010). "In this prospective study of unselected and consecutively diagnosed CRC patients, we assessed the performance of currently used clinical guidelines (AM II and RBG) against three separate molecular tumour tests (MSI, BRAF and MLH1 methylation analyses) in the identification of possible LS." (PMID 20051945, 2010). "In the one discordant case, further analyses revealed that a tumor mosaicism or multiple primary tumors were present, indicating that anti-EGFR therapy has no influence on KRAS/BRAF mutation status in mCRC." (PMID 20300583, 2009). "Seven tumours carried both KRAS and PIK3CA mutations, whereas BRAF mutations did not co-occur with the others; these frequencies closely match those in published reports and were similar between the US and Greek cohorts." (PMID 19603024, 2009). "Among 87 patients of the study population, none of 21 patients with tumours presenting whatever mutation responded to the treatment, in comparison with 22 (37%) of 60 patients with KRAS 61 and 146 and BRAF wild-type disease (P=0.0005)." (PMID 19603018, 2009). "Consistent with in vitro proliferation and in vivo tumor growth data, knock-down of BRAF, MEK1/2, and PIK3CA in IPC298 cells did not delay cell cycle progression." (PMID 19492075, 2009). "There was a trend for BRAF-positive tumours to show a shorter survival but this was not statistically significant." (PMID 18985043, 2008). "Genetic inactivation of BRAF* by doxycycline withdrawal in 4 BRAF*-driven tumors did not lead to tumor growth inhibition nor regression." (PMID 19079609, 2008). "We confirm that French and Chernobyl Tissue Bank (CTB) tumours have the same overall expression profiles and have indistinguishable BRAF and RET/PTC frequencies." (PMID 17712314, 2007).
tumor (continued). "In summary, BRAF and KRAS mutations were mutually exclusive in the morphological characteristics of colorectal nonserrated neoplasias." (PMID 16404419, 2006). "We evaluated the incidence of BRAF and KRAS mutations, high-frequency microsatellite instability (MSI-H), and the immunohistochemical status of p-MAPK in the nonserrated neoplasias (46 FDNs and 57 PNs)." (PMID 16404419, 2006). "Our results suggest that genetic differences, RET/PTC-, BRAF-related, or others, between sporadic and chPTC are not mirrored by gene expression in the tumours." (PMID 15812549, 2005). "The tumor was positive for the KRAS G12S mutation and negative for the BRAF mutation." (PMID 41589237, 2026). "Also, BRAF inhibitors result in the development of secondary keratoacanthomas and cutaneous squamous cell carcinomas, originating from a paradoxical activation of the MAPK pathway in tumor cells." (PMID 41492362, 2026). "In both cohorts, proliferating and nonproliferating CD8+ T cells were associated with similar clinicopathologic features, including proximal tumor location, lower stage, poor differentiation, absence of lymphovascular invasion, deficient MMR status, and mutant BRAF status." (PMID 41201451, 2026). "successfully employed BRAF-MEK inhibitors, specifically dabrafenib and trametinib, in the treatment of an infantile DIG presenting with leptomeningeal brainstem dissemination, this treatment approach resulted in a reduction of both residual tumor size and leptomeningeal disease burden." (PMID 41450915, 2025). "Notably, no RAS or BRAF mutation or RET fusions (analyzed by intron baiting of select genes, including RET) were encountered in the PTC tumor." (PMID 40600748, 2025). "Together, these findings suggest that the TWEAK/Fn14 axis promotes tumor progression and may represent a therapeutic target independent of RAS and BRAF mutation status." (PMID 40629930, 2025). "Furthermore, serial assessments of PD-L1 expression in larger cohorts have shown that expression levels can fluctuate over time, particularly in response to prior therapies such as anti-BRAF/MEK inhibitors, which could alter the tumor’s immunogenicity." (PMID 40002790, 2025). "Clinical routine analyses demonstrated that the tumor did not carry any BRAF alteration." (PMID 39326005, 2025). "Unlike primary tumor cells, tumor cells in brain metastases may harbor mutations in genes such as ERBB2, BRAF, MYC, and BRCA2." (PMID 39780275, 2025). "That development of one or the other tumor type is not exclusively linked to a specific mutation is supported by reports of RAS driver mutations in BRAFV600E-negative follicular-variant PTC and BRAF mutations in rare cases of FTC." (PMID 39956582, 2025). "Congruence for RAS/BRAF/PIK3CA was usually seen between cases analysed by clinical routine and with the Oncomine/WGS platforms but differed for 31 cases (5%), the choice of another sample with lower tumour cell count, or methodological issues, are possible reasons." (PMID 40437037, 2025). "Furthermore, we observed RAFi-driven activation of GCN2-ISR in tumour cells with wild type BRAF, mutant BRAF, mutant KRAS and immortalised MEFs with no ERK pathway mutation." (PMID 41249187, 2025). "Tumor tissue exhibited MSI-H, with no BRAF mutation or MLH1 promoter methylation." (PMID 41278281, 2025). "Interestingly, BRAF and KRAS mutations are mutually exclusive, meaning that they typically do not occur together in the same tumor." (PMID 40429703, 2025). "Moreover, since the tumor was BRAF-negative, no targeted treatment approaches were initially available." (PMID 39326005, 2025). "Tovorafenib demonstrated efficacy in BRAF fusion but not in NF1-LOF mutant tumor models." (PMID 40111124, 2025). "The tumor was MSI-H, with no BRAF mutation or MLH1 promoter methylation." (PMID 41278281, 2025). "In cells lacking BRAF mutations coincident ERK1/2 and GCN2-ISR activation may contribute to adventitious benign tumour growth." (PMID 41249187, 2025).